APOA1 (apolipoprotein A1)
Diseases named in the same sentence as APOA1 in open-access papers (continued):
Sharing a sentence is not in itself a finding about the gene and the disease.
Hypercholesterolemia (39 papers, 2008 to 2026). An increased concentration of cholesterol in the blood. "Among fathers with hypercholesterolemia, paternal and newborn ratio of apolipoprotein B to apolipoprotein A1 were significantly positively associated (q = 0.04)." (PMID 33849542, 2021). "A decrease in ApoA1 was associated with HDL deficiency type 2 or hypercholesterolemia more than two decades ago40; interestingly, a decrease in ApoA1 has been more recently reported to cause an impairment of the immune response against TB41." (PMID 32123229, 2020). "The consumption of black garlic increased significantly (p < 0.001) the plasma concentration of ApoA1 in both groups with a mean increase of 7.6% for the hypercholesterolemia group and 7.4% for the control group." (PMID 37513556, 2023). "Among fathers with hypercholesterolemia, paternal LLT corrected and newborn ratio of ApoB to ApoA1 were significantly positively associated (multivariable q = 0.04)." (PMID 33849542, 2021). "For an endogenous gene target for in vivo studies, we selected Apoa1, a hepatocyte-specific gene targeted for activation in therapies for hypercholesterolemia induced by high-fat diets." (PMID 31159834, 2019). "In this study, we report, for the first time, that the prevalence of high anti-ApoA-1 IgG levels in children devoid of any concomitant autoimmune diseases is substantial, reaching 38%, and seemed unrelated to familial hypercholesterolemia." (PMID 31766415, 2019). "Previous studies have demonstrated that Apolipoprotein A1 (ApoA1) and DBP are upregulated in certain diseases, including procedures involved with transplantation of bone marrow cells and in hypercholesterolemia." (PMID 18334949, 2008). "Moreover, apolipoprotein A-I (APOA1), the major protein of HDL, is strongly antiatherogenic in animal models of hypercholesterolemia." (PMID 34634315, 2021). "Along with it, she tried to get mice with hypercholesterolemia by destroying the ApoB100 and ApoA1 genes, but neither of mutants showed atheroma formation." (PMID 29151984, 2017). "With regards to lipidic parameters, all of them (LDL-C, HDL-C, TG, apoB and apoA1) were significantly higher in subjects with hypercholesterolemia, compared to non-hypercholesterolemic individuals (p < 0.001, for all); even though there was a relatively wide standard deviation in both groups." (PMID 29295555, 2017).
hypertriglyceridemia (38 papers, 2010 to 2024). A laboratory test result indicating elevated triglyceride concentration in the blood. "In previous studies, patients developed hypertriglyceridemia and showed an increase in the ApoB100/ApoA1 ratio, both atherogenic and increasing cardiovascular risk." (PMID 29535705, 2018). "The results from another study suggested that two haplotypes of the APOA1/C3/A5 gene cluster were associated with an increased risk of hypertriglyceridemia in a Taiwanese population." (PMID 26824674, 2016). "Our NGS analysis revealed 10 rare variants at 4 genes (APOA1, APOA4, APOC2, and LMF1) related to hypertriglyceridemia." (PMID 35999587, 2022). "In contrast, those found with the Milano variant of ApoA1 exhibit no increase in intima-media thickness (IMT) compared with controls despite having low HDL-C and ApoA1 levels and hypertriglyceridemia." (PMID 29986413, 2018). "The ApoA1 and ApoA4 genes have the same transcriptional direction, while ApoC3 is transcribed in the opposite direction; moreover, its polymorphic variation can lead to hypertriglyceridemia." (PMID 32795354, 2020). "APOE was identified to be essential for TG-modulating, and three genes APOA1, APOA2, and APOE were reported to be associated with hypertriglyceridemia, which may increase the risk of acute pancreatitis." (PMID 31467879, 2019). "In addition, we analyzed the frequencies of 10 variant alleles in APOA1, APOA2, APOA4, and APOA5 that have been consistently linked to hypertriglyceridemia and elevated risks of CAD." (PMID 30076208, 2018). "Lipoprotein profile, an independent risk factor of cardiovascular disease, is abnormal in CKD patients including lower HDL cholesterol, increasing the rate of apolipoprotein A1 catabolism, hypertriglyceridemia, high level of apolipoprotein B and total cholesterol but normal apo A level." (PMID 20535268, 2010). "While association with higher apoA1 and HDLC may seem contradictory to the association with high total cholesterol and hypertriglyceridemia, severe hepatic lipase deficiency is characterized by an increase in apoA1, HDLC, and HDL triglyceride content, all seen in our data as well." (PMID 36419110, 2022). "The prevalence of hypertriglyceridemia (values above the P90) was 12.0%, while low levels (below P10) of HDL-C and of apoA1 were observed in 9.0% and 10.2% of individuals, respectively." (PMID 39598108, 2024). "The serum lipid profile of these patients is characterized by hypertriglyceridemia with reduced levels of HDL and apolipoprotein A1." (PMID 29230410, 2017).
colorectal cancer (34 papers, 2011 to 2025). A primary or metastatic malignant neoplasm that affects the colon or rectum. "In colorectal cancer, the expression of ApoA1 in tumor cells is associated with different metastatic tropisms." (PMID 38212711, 2024). "A recent clinical study, which included 144 patients with colorectal cancer, revealed that low levels of serum APOA1 protein were associated with systemic inflammation, advanced stage, and unfavorable survival." (PMID 35858961, 2022). "IPA analysis correlated the inhibition of metastasis by APOA1, following the literature, which suggested that AIBP, in combination with APOA1, had an anticancer effect on colorectal cancer." (PMID 35216190, 2022). "For example, APOA family, especially APOA1, has been considered as an independent predictor for progressing cancers such as non-small cell lung adenocarcinoma, ovarian cancer, colorectal cancer and prostate cancer." (PMID 35184747, 2022). "For patients with colorectal cancer, increased APOA1 expression in the blood is concomitant with CD3+ T cells aggregation in the core of the tumor as well as the invasive margin." (PMID 36046240, 2022). "For example, apoA1 seems protective for several malignancies, but detrimental for colorectal cancer." (PMID 31936330, 2020). "APOA1 emerges as a new therapeutic option to inhibit the promotion of colorectal cancer to metastasis by modulating intracellular cholesterol metabolism." (PMID 30098223, 2018). "Another recent study reported that ApoA1 and ApoA1-binding protein suppress colorectal cancer (CRC) cell proliferation and metastasis, creating a synergistic effect against CRC migration and angiogenesis by increasing cholesterol efflux and damaging the correct distribution of invasion." (PMID 38067270, 2023). "Therefore, apabetalone, a synthetic stimulator of APOA1, is recognized as an inhibitor against colorectal cancer." (PMID 35858961, 2022). "The authors concluded that APOA1 could be a new therapeutic target for the treatment of colorectal cancer by modulating lipid metabolism." (PMID 35858961, 2022). "Several DEPs, such as APOE, APOA1, and APOL1, are known as representative HDL-associated molecules; however, they were excluded as biomarker candidates due to high fold changes observed in pancreatic or colorectal cancers." (PMID 33808296, 2021). "In this study, we analyzed the correlation between serum APOA1 and APOB levels, and APOB/APOA1 ratio, and their associations with clinicopathologic parameters, the levels of twenty systemic inflammatory markers, and survival in 144 colorectal cancer (CRC) patients." (PMID 28710487, 2017). "Apolipoprotein A1 (APOA1), located in the Ch 11q deleted region, was previously reported as an inhibitor of COX-2 expression in colorectal cancer, which results in the negative regulation of phospholipid-transporting ATPase ABCA1." (PMID 36471782, 2022). "Based on these results, we propose here, for the first time, the potential use of apabetalone, a stimulator of APOA1 so far only considered for CVD, as a bona fide inhibitor of colorectal cancer invasiveness." (PMID 30098223, 2018). "APOA1 could promote the increase of macrophage infiltration, decrease TMB and metastasis, and improve the survival rate, similar to its effects in colorectal cancer." (PMID 33509222, 2021). "Reduced ApoA1 and raised CRP have also been described in a number of systemic conditions including colorectal carcinoma, in which serum ApoA1 level showed a strong negative correlation with systemic markers of inflammation including serum CRP and serum interleukin‐8 levels." (PMID 31693246, 2020).
dementia (29 papers, 2011 to 2026). Loss of intellectual abilities interfering with an individual's social and occupational functions. "In categorical analyses limited to normal cognition elders converting to dementia over 2 years in the Sydney Memory and Ageing study, lower plasma ApoA1 levels were associated with an increased risk of dementia." (PMID 36927447, 2023). "In both MCI and dementia groups, higher plasma ApoA1 was associated with faster progression in MMSE and CDR-SB." (PMID 36927447, 2023). "We found both ApoB and the ApoB/ApoA1 ratio to be associated with higher risk of dementia only in women, and only when the follow‐up was over 20 years." (PMID 37243914, 2023). "In the Honolulu-Asia Aging Study cohort of Japanese-American men, those in the highest quarter of ApoA1 had a significantly lower risk of dementia than those in the lowest quarter." (PMID 36247924, 2022). "ApoA1 levels are also found to be significantly lower in AD patients compared to controls whereas high levels of ApoA1 are associated in lowering risks of dementia." (PMID 32456156, 2020). "Although low serum ApoA1 levels are believed to increase the risk of dementia, their relationship to post-TBI neurodegeneration has yet to be determined." (PMID 24740265, 2014). "In contrast, high levels of ApoA1 are associated with a reduced risk of dementia in older people." (PMID 41516203, 2025). "Elevated concentrations of low-density lipoprotein cholesterol (LDL-C) are linked to dementia risk, and conversely, increased plasma concentrations of high-density lipoprotein cholesterol (HDL-C) and apolipoprotein-A1 (Apo-A1) associate with decreased dementia risk." (PMID 39415269, 2024). "Similarly, in the dementia group, baseline plasma ApoA1 was also associated with MMSE decline (β − 1.55 [95% CI –3.01 to − 0.01], p = 0.048)." (PMID 36927447, 2023). "However, among normal cognition elderly subjects, the association between plasma ApoA1 and the risk of dementia is inconclusive in results from prospective and cohort studies." (PMID 36927447, 2023). "Moreover, ApoA1 and ApoA2 were independently associated with cognitive impairment and late-life dementia." (PMID 26682220, 2015). "Analysis of MCI and dementia group cognitive outcomes by APOE ε4 status revealed that higher CSF ApoA1 levels in APOE ε4 carriers had a more rapid clinical progression." (PMID 36927447, 2023). "In both MCI and dementia stages of AD, the levels of plasma ApoA1 are decreased compared to cognitive normal subjects in most studies, with few exceptions, while CSF ApoA1 is reported as unchanged or decreased between disease stages across different studies." (PMID 36927447, 2023). "Elevated plasma TG/HDL-C ratio and plasma ApoA1 are associated with worse cognitive outcomes in MCI and dementia participants." (PMID 36927447, 2023). "Now, few of them have been explored to study a possible correlation between the increased level of ApoA1 and the improvement of dementia in AD patients." (PMID 32456156, 2020). "The overexpression of human apolipoprotein A1 in the circulation may preserve cognitive function in patients with dementia partly by attenuating neuroinflammation and cerebral amyloid angiopathy." (PMID 38167163, 2024). "Among MCI, plasma/CSF ApoA1 ratio was 744.96 (SD 432.92) and dementia 957.472 (SD 606.822)." (PMID 36927447, 2023). "The MCI group in the current study had higher plasma ApoA1 levels than the Dementia group." (PMID 36927447, 2023). "Among both MCI and dementia groups, higher plasma ApoA1 had a faster rate of decline." (PMID 36927447, 2023). "The most prominent findings of our present study were newly found increases in HDL-4 variables (ApoA1 apolipoprotein, free cholesterol, and cholesterol) in both dementia groups and changes in triglycerides (VLDL, including VLDL-1 and VLDL-2, and IDL) that were higher in AD specimens." (PMID 36293327, 2022).
dementia (continued). "Among dementia APOE ε4 carriers, higher CSF ApoA1 also had a faster rate of decline in MMSE (β − 1.03 [95% CI, − 1.95 to − 0.11], p = 0.029)." (PMID 36927447, 2023). "Here we evaluate baseline plasma TG/HDL-C ratio and CSF and plasma ApoA1 levels and their relation with cognitive decline in the MCI and Dementia stages of AD." (PMID 36927447, 2023). "Among dementia APOE ε4 carriers, higher plasma TG/HDL-C had a faster rate of decline in CDR-SB and higher plasma ApoA1 had a faster rate of decline in MMSE." (PMID 36927447, 2023). "Higher plasma ApoA1 in dementia APOE ε4 non-carriers also related to faster decline in LM scores (β − 2.75 [95% CI, − 4.27 to − 1.24], p < 0.001)." (PMID 36927447, 2023). "The only non-significant comorbidities were HIV (p = 0.52) and dementia (p = 0.14) for the apoA1 group, presumably due to the small sample sizes (both n < 20)." (PMID 37372137, 2023). "Third, the current study has no the follow-up data to determine whether baseline apolipoprotein A1 levels is a conceivable predictor for the incidence of dementia in patients with T2DM." (PMID 38167163, 2024). "The results for plasma ApoA1 were significant for both APOE ε4 carriers and non-carriers in the MCI and dementia groups for at least one of the three cognitive measures tested (MMSE, CDR-SB, and LM)." (PMID 36927447, 2023). "CSF ApoA1 was positively correlated to CSF Abeta 42 levels in MCI (r = 0.36, p < 0.001) and had borderline significance for dementia (r = 0.32, p = 0.069) but not p-tau181 or total-tau." (PMID 36927447, 2023). "In the dementia group, CSF ApoA1 levels correlated positively with CSF ICAM1 and VACM1 levels [correlation range 0.55 to 0.62, all p < 0.001], while a negative correlation was observed between plasma ApoA1 and CSF ICAM1 and VCAM1, but this correlation was not significant." (PMID 36927447, 2023).
gastric cancer (28 papers, 2012 to 2025). A primary or metastatic malignant neoplasm involving the stomach. "APOA1 mRNA and serum APOA1 protein are potential diagnostic and prognostic biomarkers for gastric cancer." (PMID 40823076, 2025). "Our results show that the presence of APOE ε2 allele and low serum levels of total cholesterol, HDL-cholesterol, apoA1 and apoA1/B ratio are associated with an increased risk of gastric cancer." (PMID 26817942, 2016). "The APOE ε2 allele affects different lipid metabolism markers across various tumors, ApoA1 levels are significantly increased in patients with early-stage gastric cancer, whereas they remain relatively stable in those with advanced-stage gastric cancer." (PMID 39763652, 2024). "Similar to apolipoprotein A1, HDL cholesterol is inversely associated with cancers, as demonstrated in the subset gastric cancer in this study." (PMID 38263244, 2024). "A low level of plasma APOA1 was found to have potential utility as a blood-based biomarker for detecting gastric cancer progression and distinguishing malignant from benign conditions." (PMID 37999824, 2023). "Clinical studies have shown that the level of ApoB/ApoA1 in gastric cancer patients is negatively correlated with the survival rate, while PDIA4 is positively correlated with the survival rate of gastric cancer patients." (PMID 34476221, 2021). "Previous literature has also reported that ApoB/ApoA-1 is an independent prognostic factor for gastric cancer." (PMID 32391278, 2020). "Another highly downregulated gene we found in Myd88−/− mice infected with H. felis was Apoa1, which was also reported to be downregulated in a fast progressing gastric cancer mouse model." (PMID 28201999, 2017). "For example, decreased APOA1 serum levels have been reported in patients with ovarian, pancreatic, and gastric cancer as well as lymphoblastic leukemia." (PMID 23118872, 2012). "Moreover, the expression of APOA1 and CGA was associated with poorer prognosis in gastric cancer from the TCGA dataset, and CGA is a typical marker of NECs." (PMID 36729271, 2023). "The results of some meta-analyses suggest that low levels of APOA1 may be a poor prognostic indicator for various malignancies, including non-small cell lung cancer, gallbladder cancer, and gastric cancer." (PMID 35421932, 2022). "Proteomics approach in human gastric cancer also showed downregulation of Apoa1, but its role in gastric carcinogenesis is unknown." (PMID 28201999, 2017). "In this multivariable analysis, there was still strong evidence of an association with increased risk of gastric cancer for age (P < 0.0001), BMI (P < 0.0001), total cholesterol (P < 0.0001), HDL-cholesterol (P < 0.0001), apoA1 (P < 0.0001), and apoA1/B ratio (P < 0.0001)." (PMID 26817942, 2016). "Consistent with the preceding analytical results, the expression of APOA1, BCHE, and STARD5 in human gastric cancer cells (AGC, HGC-27) was significantly lower (p<0.0001) compared to normal gastric epithelial cells (GSE-1)." (PMID 38357546, 2024). "These aptamers were used for detecting APOA1, Importin subunit alpha-1, PARD3, and APOA4 gastric cancer biomarkers; where Importin subunit alpha-1 is the strongest candidate to be used for further gastric cancer diagnosis." (PMID 32659966, 2020). "Additionally, risk of gastric cancer was significantly higher for individuals with lower levels of triglycerides (P < 0.0001), total cholesterol (P < 0.0001), HDL-cholesterol (P < 0.0001), LDL-cholesterol (P < 0.0001), apoA1 (P < 0.0001), and apoB (P < 0.0001)." (PMID 26817942, 2016). "Low expression of apolipoproteins including APOA1, APOA2, APOA4 and APOC3 in plasma exosomes of patients with hepatic-specific metastasis indicated an impaired function of lipid metabolism, which could participate in hepatic metastasis in gastric cancer cells." (PMID 37568802, 2023).